LAMB3 (laminin subunit beta 3)
Diseases named in the same sentence as LAMB3 in open-access papers (continued):
Sharing a sentence is not in itself a finding about the gene and the disease.
cervical carcinoma (11 papers, 2011 to 2025). A carcinoma arising from either the exocervical squamous epithelium or the endocervical glandular epithelium. "For example, combinations of genetic polymorphisms such as Pre-miR-218 expression and the methylation of C13ORF18/DAPK substantially elevated cervical cancer risk compared to profiles involving LAMB3 alone." (PMID 40649795, 2025). "Polymorphism genes such as CD28 (rs3116496), IFNG (rs2430561), Pre-miR (rs11134527), and LAMB3 (rs2566), along with DNA-repairing SNPs, affect individual susceptibility to cervical cancer." (PMID 40649795, 2025). "Our study concluded LAMB3 as a potential target gene associated with the survival of cervical cancer patients." (PMID 36305754, 2023). "In this case–control study of 1,584 cervical cancer cases and 1,394 cancer-free female controls, we investigated associations between two miR-218-related SNPs involved in the LAMB3-miR-218 pathway and the risk of cervical carcinoma in Eastern Chinese women." (PMID 23320911, 2013). "Our findings suggest some possible interactions between genetic variations involved in the LAMB3-miR-218 pathway and other risk factors for cervical carcinoma." (PMID 23320911, 2013). "In this relatively large hospital-based case–control study of 1,584 cervical cancer cases and 1,394 cancer-free female controls, we validated two previously reported significant miRNA-related SNPs involved in the LAMB3-miR-218 pathway for the risk of cervical carcinoma in Chinese populations." (PMID 23320911, 2013). "To date, only two reported studies have investigated the associations between three miRNA-related SNPs and the risk of cervical carcinoma, two of which (i.e., pri-miR-218 rs11134527 and LAMB3 rs2566) are found to be associated with altered risk of cervical cancer in a Chinese Han population." (PMID 23320911, 2013). "To further test the hypothesis that miRNA-related SNPs involved in the LAMB3-miR-218 pathway contribute to cervical cancer risk, we performed a case–control study with a much larger sample size to validate the reported associations with cervical cancer risk in Eastern Chinese women." (PMID 23320911, 2013). "The invasion capacity of both cervical cancer cells was significantly decreased in LAMB3 siRNA knockdown when compared to NTC." (PMID 38473784, 2024). "The current study aimed to investigate the functional role of LAMB3 in cervical cancer progression using HPV16-positive cervical cancer cell lines (CaSki and SiHa)." (PMID 38473784, 2024). "The siRNA concentration of 20 pmole/well of a 24 well-plate with transfection for 72 h was appropriate for silencing of LAMB3 mRNAexpression in both the SiHa and CaSki cervical cancer cell lines." (PMID 38473784, 2024). "KEGG pathway analysis showed that the upregulated LAMB3 in cervical cancer samples is involved in many significant pathways, such as pathways in cancer and the PI3K-AKT signaling pathway." (PMID 38473784, 2024). "The present study showed that LAMB3 was upregulated in cervical cancer samples and was involved in the PI3K-AKT signaling pathway, which was previously reported to have carcinogenesis involvement in other cancer cells." (PMID 38473784, 2024). "The laminin subunit beta-3 (LAMB3) mRNAwas overexpressed in cervical cancer and was chosen for functional analysis." (PMID 38473784, 2024). "This study is the first to demonstrate that LAMB3 downregulation affects the significant characteristics of HPV16-positive cervical cancer cells, including decreased migration, invasion and metastasis." (PMID 38473784, 2024). "The present study demonstrated that colony formation was significantly decreased after LAMB3 siRNA knockdown in both cervical cancer cell lines." (PMID 38473784, 2024). "We investigated the influence of LAMB3 on the colony formation capacity of SiHa and CaSki cervical cancer cell lines." (PMID 38473784, 2024).
cervical carcinoma (continued). "The results of survival analysis demonstrated that LAMB3 is correlated with the survivability of patients diagnosed with cervical cancer negatively, and acts as a carcinogen in cervical cancer." (PMID 36305754, 2023). "Our experimental results indicated that overexpression of LAMB3 can reverse the inhibition of cervical cancer cell proliferation and invasion induced by hsa‐mir‐133a‐2." (PMID 36305754, 2023). "The luciferase activity of the cervical cancer cells that co‐transfected with LAMB3‐WT as well as hsa‐mir‐133a‐2 inhibitor was increased greatly." (PMID 36305754, 2023). "Hsa‐mir‐133a‐2 inhibits PI3K / Akt pathway by targeting LAMB3, and then inhibits the proliferation and invasion of cervical cancer cells." (PMID 36305754, 2023). "As a result, hsa‐mir‐133a‐2 suppresses cervical cancer progression by means of inhibiting PI3K/AKT signaling pathway mediated by LAMB3." (PMID 36305754, 2023). "LAMB3 expression in cervical cancer tissues is noticeably higher than in adjacent paracancerous tissues." (PMID 36305754, 2023). "Our study results demonstrated that the luciferase activity of cervical cancer cells co‐transfected with LAMB3‐WT and hsa‐mir‐133a‐2 was significantly reduced compared to the NC control group." (PMID 36305754, 2023). "By blocking the PI3K/AKT signaling pathway mediated by LAMB3, hsa‐mir‐133a‐2 can inhibit cervical cancer cell proliferation and invasion." (PMID 36305754, 2023). "Downregulation of LAMB3 by miR-218 was also reported in cervical carcinoma cells by conducting qRT-PCR and western blot analyses." (PMID 23159910, 2012). "The functional results could indicate that LAMB3 upregulation in both cervical cancer cell lines (SiHa and CaSki) plays a major role in promoting cervical cancer cell invasion and migration but has little effect on cervical cancer cell proliferation." (PMID 38473784, 2024). "LAMB3 has been shown to be elevated in various cancers, including cervical cancer." (PMID 38473784, 2024). "Cervical cancer cell lines with LAMB3 siRNA knockdown showed decreased hallmarks of cancer properties, such as cell proliferation, migration and invasion, that might be associated with downregulation of proteins involved in the PI3K/AKT signaling pathway." (PMID 38473784, 2024). "This study demonstrated that LAMB3 could promote cervical cancer cell migration, invasion and survival." (PMID 38473784, 2024). "This indicates that LAMB3 upregulation enhanced clonogenic potential and self-renewal ability and might be involved in anoikis resistance properties in cervical cancer cell lines." (PMID 38473784, 2024). "This indicated that LAMB3 knockdown had an effect on cervical cancer cell survival." (PMID 38473784, 2024). "Meanwhile, there is a negative correlation between the expression levels of hsa‐mir‐133a‐2 and LAMB2, and LAMB3 could reverse hsa‐mir‐133a‐2 inhibitory effect on cervical cancer cell proliferation and invasion." (PMID 36305754, 2023). "In summary, hsa‐mir‐133a‐2 could inhibit the pathway of PI3K/AKT by targeting LAMB3 in cervical cancer, thereby inhibiting cervical cancer cell proliferation and invasion." (PMID 36305754, 2023). "The overexpression of hsa‐mir‐133a‐2 inhibited the proliferation of siha and caski cells, according to CCK‐8 results, however, the upregulation of LAMB3 expression significantly decreased the inhibitory effect of hsa‐mir‐133a‐2 on cervical cancer cell proliferation (p < 0.05)." (PMID 36305754, 2023). "Based on such results, it is speculated that hsa‐mir‐133a‐2 may regulate the pathway by targeting LAMB3, thus affecting cervical cancer cell proliferation and invasion." (PMID 36305754, 2023). "hsa‐mir‐133a‐2 inhibits cervical cancer cell proliferation and invasion by targeting LAMB3." (PMID 36305754, 2023).
cervical carcinoma (continued). "Our study is the first study to research and evaluate the regulatory role that hsa‐mir‐133a‐2 plays in the development and progression of cervical cancer and to explore the regulatory mechanism of the hsa‐mir‐133a‐2/LAMB3 in the progression of cervical cancer preliminarily." (PMID 36305754, 2023). "In addition, the anti-oncogene function of miR-218 has been reported in several types of cancers through targeting several oncogenes, such as Rictor (oral cancer), EGFR (non-small cell lung cancer), ROBO1 receptor (gastric cancer) and LAMB3 (cervical cancer)." (PMID 29152130, 2017). "In cervical cancer, miR-218 involves in focal adhesion pathway by directly targeting LAMB3." (PMID 26610476, 2015). "LAMB3 expression levels and hsa‐mir‐133a‐2 levels in cervical cancer cells were adjusted to evaluate whether LAMB3 has an effect on hsa‐mir‐133a‐2's role in cervical cancer cells." (PMID 36305754, 2023). "However, for the other SNP (i.e., LAMB3 rs2566), our data did not have statistical evidence to support its association with cervical cancer risk." (PMID 23320911, 2013). "Moreover, LAMB3 increased expression levels of the HPV16 E6 oncoprotein in cervical cancer cells and this process might be mediated by miR-218, which indicates a possible mechanism of the LAMB3-miR-218 pathway involved in the development of cervical carcinoma." (PMID 23320911, 2013). "We selected to explore the underlying mechanism of LAMB3's role in the proliferation and invasion of cervical cancer cells, and our study performed KEGG pathway enrichment analysis on the differential genes within high/low expression LAMB3 group." (PMID 36305754, 2023). "That is, the higher the level of LAMB3 expression, the shorter the progression‐free survival period (PFS)and OS of cervical cancer patients." (PMID 36305754, 2023). "One study reported that LAMB3 was highly expressed in HPV16-positive cervical cancer cell lines (SiHa), and laboratory investigations revealed that HPV16E6 protein induced the expression of LAMB3, while miR-218 expression in the SiHa cell line inhibited LAMB3 protein expression." (PMID 38473784, 2024). "miR‐218′s direct target is LAMB3, and the changes in the expression of the two could promote the infection of the HPV virus to the surrounding tissues of the lesion, resulting in cervical cancer." (PMID 36305754, 2023). "Moreover, the LAMB3 was able to up‐regulate the phosphorylation levels of AKT and phosphatidylinositol 3‐kinase (PI3K) protein in cervical cancer cells." (PMID 36305754, 2023).
colorectal cancer (11 papers, 2017 to 2025). A primary or metastatic malignant neoplasm that affects the colon or rectum. "One study of colorectal cancer reported that LAMB3 overexpression was activated by BRD2/acetylated ELK4 complex; furthermore, LAMB3 overexpression activated AKT and resulted in degradation of FOXO3/4, a tumor suppressor protein." (PMID 38473784, 2024). "In previous studies, LAMB3 has been reported to interact with LAMC2 to form the β3γ2 heterodimer in the cytoplasm of colorectal cancer cells and thus contribute to cancer cell budding." (PMID 36612197, 2022). "An interesting example is LAMB3, which is overexpressed in colorectal cancer (CRC) and is correlated to tumor metastasis and poor prognosis." (PMID 35163690, 2022). "It has been reported that LAMB3 overexpression is a marker of poor prognosis in colorectal cancer, and that LAMB3 promotes migration in vitro and tumor growth and metastasis in vivo." (PMID 34151031, 2021). "PIGR suppresses colorectal cancer through the AKT-FOXO3/4 axis by downregulating LAMB3 expression, which may provide a clue for molecular treatment for CRC." (PMID 35992840, 2022). "In conclusion, MDFI promotes the proliferation and tolerance to chemotherapy of colorectal cancer cells, partially through the activation of the AKT signaling pathway by the binding to ITGB4/LAMB3." (PMID 38375821, 2024). "miR-1298 acts a tumor suppressor in KRAS-driven NSCLC and colorectal cancer cells by directly targeting the mRNA of both FAK and the Laminin subunit beta 3 (LAMB3), lowering their protein expression levels." (PMID 29891810, 2018). "For example, LAMB3 was correlated with chemoresistance and poor prognosis in Stage III colorectal cancer." (PMID 29404274, 2017). "In previous studies, LAMB3 was also reported to promote tumor progression and chemoresistance through the AKT-FOXO3/4 axis and be transcriptionally regulated by the BRD2/acetylated ELK4 complex and polymeric immunoglobulin receptor in colorectal cancer." (PMID 36612197, 2022).
lung carcinoma (10 papers, 2017 to 2025). "In a heat map, we explored the top 50 co-expressed genes that were either positively or negatively associated with LAMB3 expression in lung cancer." (PMID 37577750, 2023). "In conclusion, further investigation of LAMB3 in lung cancer and its significance in pan-carcinoma diagnosis and prognosis can contribute new perspectives to a comprehensive comprehension of its crucial role in tumor progression." (PMID 37577750, 2023). "In particular, LAMB3 expression levels were found to have a strong correlation with all aspects of lung cancer." (PMID 37577750, 2023). "Experiments showed that the protein expression level of LAMB3 in lung cancer cell lines A549 and H1299 was significantly higher than that in normal lung epithelial cells BEAS-2B." (PMID 37577750, 2023). "We investigated the connection between the amount of infiltration of 26 immune-related cells and the level of LAMB3 expression in lung cancer." (PMID 37577750, 2023). "LAMB3 gene expression levels were higher in 8 cases of lung cancer and 4 lung cancer cell lines (lung scale/lung adenocarcinoma) than in paracarcinous tissue or normal lung epithelial cells." (PMID 37577750, 2023). "The results showed that inhibition of LAMB3 expression significantly inhibited the migratory ability of lung cancer cells, which was statistically significant." (PMID 37577750, 2023). "In the majority of cancers, including lung cancer, LAMB3 expression was negatively correlated with T cells, B cells, and macrophages." (PMID 37577750, 2023). "The effect of LAMB3 on the migration ability of lung cancer cell lines A549, A549-siLAMB3, H1299, and H1299-siLAMB3 was analyzed in wound healing assays." (PMID 37577750, 2023). "LAMB3’s high expression is consistent with the expression trends we find in lung cancer cell lines and the tissues of lung cancer patients." (PMID 37577750, 2023). "LAMB3 expression was associated with TMB in 33 cancer types and MSI in 32 cancer types, while in lung cancer LAMB3 expression was strongly associated with immune cell infiltration and negatively correlated with all seven methylated CpG islands." (PMID 37577750, 2023). "The expression of LAMB3 in lung cancers with various clinical features was then further investigated." (PMID 37577750, 2023). "We further used ROC curves to assess the accuracy of LAMB3 in predicting OS in lung cancer patients." (PMID 37577750, 2023). "We performed further analysis of the co-expressed genes of LAMB3 in lung cancer." (PMID 37577750, 2023). "In most cancers, including lung cancer, LAMB3 expression was positively correlated with NK cells." (PMID 37577750, 2023). "LAMB3 genomic alterations in lung cancer were explored via the cBioPortal website." (PMID 37577750, 2023). "Studies have found that LAMB3 may participate in invasion and metastasis ability of some cancers, like thyroid, liver, and lung cancers." (PMID 37214471, 2023). "Furthermore, at the cellular level, we found that reducing LAMB3 expression in lung cancer cell lines A549 and H1299 inhibited the proliferation, migration, and invasive ability of tumor cells." (PMID 37577750, 2023). "Finally, we explored differences in LAMB3 expression and prognosis in lung cancer to further verify their outcomes in human cancers." (PMID 37577750, 2023). "Interestingly, two of the NRF2 target genes involved in ECM-receptor interactions – osteopontin (secreted phosphoprotein 1) and LAMB3 (laminin subunit beta 3) – have been identified as crucial pro-metastatic genes for lung cancer." (PMID 29050246, 2017). "In primary lung cancers, LAMB3 is upregulated; the high expression positively correlates with the grade of malignant differentiation, advanced tumour stage, lymphatic lung tumour metastasis, and the enhanced migration and infiltration of lung cancer cell lines." (PMID 41139196, 2025).
lung carcinoma (continued). "Furthermore, LAMB3 expression was correlated with all marker genes for other cytokines that are known to be immunostimulatory and immunosuppressive, indicating that LAMB3 may play an immune function in lung cancer and other cancers." (PMID 37577750, 2023). "The authors reported that osteopontin, LAMB3 and ITGB1 are pro-metastatic genes for lung cancer." (PMID 28871224, 2017). "In other investigations, anti‐LM332 antibodies suppress metastases of LM332‐expressing squamous carcinoma, 40 and knockdown of genes expressing either the laminin β3 41 or γ2 42 chains of LM332 (LAMB3, LAMC2, respectively) in lung carcinoma cells decreases their metastatic potential." (PMID 27878981, 2017).
pancreatic ductal adenocarcinoma (8 papers, 2019 to 2025). An infiltrating adenocarcinoma that arises from the epithelial cells of the pancreas. "This synergism has significant anti-cancer effects on pancreatic ductal adenocarcinoma via targeting EGFR-signaling through Laminin subunit beta 3 (LAMB3) regulation." (PMID 40490812, 2025). "miR-24-3p inhibits the progression of pancreatic ductal adenocarcinoma by decreasing LAMB3 expression levels." (PMID 34511042, 2021). "In pancreatic ductal adenocarcinoma (PDA), miR-24-3p exerted its anti-cancer role by suppressing the expression of Laminin Subunit Beta 3 (LAMB3), an oncogene." (PMID 33123467, 2020).
prostate carcinoma (8 papers, 2018 to 2025). A carcinoma that arises from epithelial cells of the prostate gland. "In terms of proliferation, invasion, migration and apoptosis rates, LAMB3 expression levels were inversely correlated with prostate cancer progression, showing statistically significant differences." (PMID 41343534, 2025). "It has been reported that LAMB3 is involved in the invasive and metastatic abilities of some types of cancer, such as colon, pancreas, lung, cervix, stomach, and prostate cancer." (PMID 35033172, 2022). "Laminin subunit beta-3 (LAMB3) relates to the invasion and metastasis of certain cancers, such as colon, pancreatic, pulmonary, cervical, gastric, and prostate cancer." (PMID 34903206, 2021). "The hub genes in the “PRAD: magenta” module were identified to be abnormally expressed in prostate cancers, such as LAMB3 and ST6GALNAC2." (PMID 30181502, 2018). "Finally, we overexpressed and knocked down LAMB3 in prostate cancer cells using lentiviral plasmid transfection, followed by functional experiments to validate LAMB3 as a tumor suppressor gene that inhibits prostate cancer progression." (PMID 41343534, 2025). "In contrast, the H3 A subtype increases LAMB3 expression but also fails to assemble laminin 5, further driving prostate cancer progression." (PMID 41343534, 2025). "In addition, LAMB3 is involved in the invasive and metastatic abilities of some types of cancer, including colon, pancreas, lung, cervix, stomach, and prostate cancer, but the role and mechanism of LAMB3 in PDAC have not been previously determined." (PMID 30850586, 2019).